BRCA1 (BRCA1 DNA repair associated)
Diseases named in the same sentence as BRCA1 in open-access papers (continued):
Sharing a sentence is not in itself a finding about the gene and the disease.
cancer (continued). "Haploinsufficiency is thought to predispose these women to cancer by reducing the pool of available BRCA1 transcript and protein, thereby compromising BRCA1 function." (PMID 27534398, 2016). "In early studies, including a small number of tumor samples obtained from large BC and OC families, it was suggested that greater than 85 % of BRCA1- or BRCA2-associated cancers exhibited LOH, and all showed loss of the normal allele." (PMID 27836010, 2016). "FA proteins and another breast/ovarian cancer susceptibility protein, BRCA1, cooperate in a DNA repair pathway, which is required for resistance to DNA interstrand crosslinks." (PMID 26967246, 2016). "For haploinsufficiency to be an early driver of BRCA1-associated cancer development, mutation-dependent reduction in BRCA1 expression levels should be associated with a loss of function." (PMID 27534398, 2016). "PARP1 inhibitors have been used to induce synthetic lethality in tumors harboring BRCA1/2 mutations presumably by elevation of the number of DSBs in HR-impaired cancer cells." (PMID 26784987, 2016). "Its initial trial as monotherapy agent demonstrated its preferential effect towards cancers arising in BRCA1/2 germ-line mutation carriers." (PMID 27555886, 2016). "With this, we would like to explain the cancer risk modifier effect that this gene exerts in carriers of BRCA1 and BRCA2 mutations." (PMID 27015555, 2016). "As Sanger sequencing is the most frequently used method to screen BRCA1 gene in patients and individuals in risk of cancer, this technique would miss the majority of BRCA1 low rate mosaic mutations." (PMID 26481646, 2016). "Accordingly, cancers containing mutations in BRCA1 have numerous copy number aberrations (CNAs) and are more likely to be TNBC or HGS-OvCa." (PMID 27213343, 2016). "Careful cancer screening on the family members of any detected pathogenic germline BRCA1/2 mutation should be advised." (PMID 27907908, 2016). "The increased cancer susceptibility in BRCA1 and BRCA2 mutation carriers therefore can—to a large extent—be explained by chromosomal instability." (PMID 27881737, 2016). "Women with hereditary mutations in the BRCA1 or BRCA2 (BRCA1/2) genes have an increased risk of several cancers, including EOC." (PMID 29670811, 2016). "Mutations in the BRCA1/BRCA2 genes have also been associated with inherited predisposition to other cancers in HBOC families, like those of the prostate, pancreas, male breast, peritoneum, and fallopian tube." (PMID 27532258, 2016). "Silencing of BRCA1 was linked to increased risk of several types of cancer, which are not limited to breast or ovarian types, but also include cervical, pancreatic, uterine, colon, and prostate cancers." (PMID 27356740, 2016). "Several prediction models, which consider age of onset and family history of cancer, can be used to estimate the prior probability of having a BRCA1 or BRCA2 mutation." (PMID 27553291, 2016). "Abnormal pancreatic imaging findings including pancreatic atrophy, cysts, ductal dilation, or cancer were identified in 35% of patients with known at-risk BRCA1 and BRCA2 genetic mutations." (PMID 27069714, 2016). "Clinical mutation screening of the cancer susceptibility genes BRCA1 and BRCA2 generates many unclassified variants (UVs)." (PMID 26913838, 2016). "We describe the design and analytic validation of the Counsyl Inherited Cancer Screen, a next-generation-sequencing-based test to detect pathogenic variation in the BRCA1 and BRCA2 genes." (PMID 27375968, 2016). "BRCA1/2 germline mutation carriers have an elevated cancer risk restricted to breast and reproductive organs in spite of the fact that the encoded proteins are expressed in nearly every tissue." (PMID 27216078, 2016). "A weak, but significant association of high (3+) nuclear PARP1 expression was observed with BRCA1-mutated/-methylated cancers compared with wildtype TNBC specimens (50 % vs. 18 %, p = 0.016; n = 62)." (PMID 27756336, 2016).
cancer (continued). "At the PARP inhibitory concentration, 7-methylguanine itself wasnot cytotoxic, but it was able to accelerate apoptotic death of BRCA1-deficientbreast cancer cells induced by cisplatin and doxorubicin, the widely usedDNA-damaging chemotherapeutic agents." (PMID 27437145, 2016). "UPA is already used and well tolerated in clinics although further studies are needed to test its potential to decrease cancer risk in women with BRCA1 mutations." (PMID 27246982, 2016). "The dramatic positive therapeutic effect (pCR) of cisplatin treatment in patients carrying BRCA1-associated cancers has been generally attributed to germline BRCA1 mutations and to the dysfunction of DNA damage repair by HR." (PMID 27626685, 2016). "Apart from founder mutations in Polish cancer patients, several other recurrent BRCA1 (185delAG, 3819del5, 3875del4, 5370C > T) and BRCA2 (886delGT, 4075delGT, 5467insT, 6174delT, 8138del5) mutations were detected." (PMID 26779294, 2016). "Here, we describe the design and analytic validation of the Counsyl Inherited Cancer Screen, a next-generation-sequencing-based test to detect pathogenic variation in the BRCA1/2 genes." (PMID 27375968, 2016). "Most likely being of great advantage for the majority of cancers, metformin appears to be particularly well suited for the needs of BRCA1 germline mutation carriers for the following reasons." (PMID 27590516, 2016). "Specific inherited mutations in BRCA1 increase the risk of breast and ovarian cancers, and it has been associated with increased risks of several additional types of cancer." (PMID 27179759, 2016). "Astonishingly, while the chemonaive carcinomas showed LOH characteristic for BRCA1-associated malignancies, the wild-type allele was preserved in the residual tumor masses removed upon surgery." (PMID 27555886, 2016). "Recently, the emergence of NGS techniques has played an important role in the simultaneous screening of multiple cancer susceptibility genes including the BRCA1 and BRCA2 genes." (PMID 26221963, 2015). "This rate is comparable to cancer detection rates in the high risk BRCA1 and BRCA2 mutation carrier population, for whom screening breast MRI has indeed been found to be useful and is an imaging modality recommended for wide usage." (PMID 26322264, 2015). "The association of ‘early’ FA genes with FANCD2 monoubiquitination defects with increased cancer susceptibility is much weaker compared with the ‘late’ FA genes such as BRCA1, BRCA2, BRIP1, PALB2 and RAD51C." (PMID 26085575, 2015). "This cell is the likely ‘cell of origin’ for basal-like cancers that arise in BRCA1 mutation carriers." (PMID 26080807, 2015). "Several cancer drugs have been identified that exhibit synthetic lethality with specific tumor suppressors, most notably BRCA1 mutation/PARP inhibitors." (PMID 25970771, 2015). "It was firstly studied in patients with BRCA1/2 mutations and sporadic cancers associated with HR repair defects." (PMID 26610585, 2015). "We detected 53 BRCA1 rare truncation variants across 7 cancer types and 50 BRCA2 rare truncation variants across 6 cancer types." (PMID 26689913, 2015). "For example, the commonly used cancer biomarkers prostate-specific antigen for prostate cancer and BRCA1/2 gene mutations for breast cancer can identify only about 25 % and 10 % to 25 % of the patients in each cancer type, respectively." (PMID 26391980, 2015). "Largely characterized in cancer, the breast cancer susceptibility gene, BRCA1, is a tumor suppressor protein that has implications in processes such as cell cycle, DNA repair, and transcription." (PMID 25879655, 2015). "A recent report using targeted gene panel testing provided similar cancer risk PPVs in 10.6% [95% CI: 6.1–16.9%] of non-BRCA1/2 patients." (PMID 26023681, 2015).
cancer (continued). "CIMBA is a collaborative group of researchers working on genetic modifiers of cancer risk in BRCA1 and BRCA2 mutation carriers." (PMID 25925750, 2015). "KSR1 expression is positively associated with breast cancer 1, early onset (BRCA1), BRCA1-associated ring domain 1 (BARD1) and checkpoint kinase 1 (Chk1) levels in breast cancer specimens." (PMID 26425651, 2015). "Knowledge of the presence of a BRCA1 mutation is important for both prevention of cancer and personalized treatment." (PMID 26468334, 2015). "Inhibiting PARP activity uncovers potential of PARP inhibitors as promising candidates for cancer therapy, particularly in BRCA1/2 mutated cancers, alone or in combination with cytotoxic drugs." (PMID 25606064, 2015). "A recent report demonstrated that Etoposide induces ZFP36 expression and, moreover, it is interesting to note that ZFP36 levels rise in response to the “breast cancer susceptibility protein” BRCA1, which is implicated in the DNA damage response." (PMID 25939870, 2015). "We calculated the change in population cancer incidence over time based on the number of BRCA1/2 mutation carriers we identified and the rate of prophylactic surgeries done to identify opportunities to improve cancer prevention." (PMID 26870808, 2015). "ER-negative status has been suggested to be intrinsic to BRCA1-related cancer as it has been found that the proportion of ER-negative patients with BRCA1 mutations was significantly higher than for ER-positive patients." (PMID 26221963, 2015). "Sufficient information to conclude on potential presence of triple negativity was available in 29 of 38 BRCA1 associated cancers." (PMID 26029931, 2015). "The BRCA1+ group was the only one where p.Val660Leu polymorphism in the PGR gene had any impact on cancer risk." (PMID 25591549, 2015). "Interfering with this cycle is protective against such cancers even in individuals with hereditary predisposition including BRCA1 mutation carriers." (PMID 26488398, 2015). "To accomplish this task, we developed a new molecular toolkit using patient-derived cancer cells that produce the breast cancer susceptibility protein, BRCA1." (PMID 26395823, 2015). "A number of studies indicated BRCA1/2 gene mutations are associated with familial aggregation of cancer." (PMID 26236408, 2015). "The low presence of BRCA1 mutated cancer in our study and the different antibody used are possible reasons for discrepancies between these results." (PMID 26312763, 2015). "Mutation of TP53BP1 for instance, reverses the HR defect in BRCA1 mutant cancers and render these cancers resistant to PARP1 inhibition." (PMID 25852742, 2015). "Nonetheless, some studies have suggested that only a very small proportion of early-onset cancer in the general population is attributed to BRCA1/2 gene mutations." (PMID 26236408, 2015). "A strong link exists between BRCA1 mutations and basal phenotype, with 80–90 % of BRCA1 cancers expressing this phenotype." (PMID 26152113, 2015). "Our current analysis on TRs indicated opposing roles of TRα and TRβ on survival of women carrying a BRCA1 germline mutation and on target gene activation in BRCA1 mutant cancer cells." (PMID 26029931, 2015). "One of the major advancements in cancer research was the discovery of the breast cancer susceptibility gene 1 (BRCA1) and the breast cancer susceptibility gene 2 (BRCA2)." (PMID 26236408, 2015). "Previous studies have highlighted an association with BRCA1/2 gene mutations and an increased risk of developing cancer in sites other than the breast and ovary." (PMID 26236408, 2015). "As mutations in checkpoint and DNA repair pathways are associated with cancer, tumor cells defective in HR repair with diminished or ablated BRCA1/2 gene function, show extensive DNA repair lesions and are more sensitive to PARP inhibitors." (PMID 25868852, 2015).
cancer (continued). "After excluding GEN1 from the analysis, the WGS data identified six individuals in the BRCA1/2 cohort with LoF PPVs in four dominant cancer-associated genes, in addition to their clinically diagnosed BRCA1/2 mutation." (PMID 26023681, 2015). "Examples of BRCA1 mutation carriers were found among women with serous, endometrioid and mixed cell subtype cancers in contrast to BRCA2 mutation carriers, who were found to have had either serous or undifferentiated adenocarcinomas." (PMID 25884701, 2015). "Recent studies have highlighted importance of RAD52 in human cancer cell lines deficient in BRCA1, PALB2 or BRCA2, as its depletion led to cell death in a synthetic lethality manner." (PMID 26610585, 2015). "TRβ remained to be a positive prognostic factor in BRCA1 mutated cancers classified as NST (p = 0.036), high grade (p = 0.018), ER negative (p = 0.020) or PR negative (p = 0.029)." (PMID 26029931, 2015). "As cancers in BRCA1 and BRCA2 mutation carrier subjects occur at an earlier age, identification, education and implementation of risk reduction has a high cost-to-benefit ratio in favor of benefit." (PMID 26543556, 2015). "Numerous studies have established that cancers with a dysfunction of the HR DNA repair pathway, also referred to as “BRCAness,” share characteristics with BRCA1- or BRCA2-mutated cancer cells and are very sensitive to PARPi." (PMID 26497583, 2015). "BRCA1 down-regulation has been implicated in the development of a cancer stem cell-like phenotype in breast cells." (PMID 26379698, 2015). "One of the limitations of PARP therapy is that there are limited numbers of cancer patients with BRCA1 or BRCA2 mutation." (PMID 25769025, 2015). "Although BRCA1 function is essential for maintaining genomic integrity in all cell types, it is unclear why increased risk of cancer in individuals harbouring deleterious mutations in BRCA1 is restricted to only a select few tissues." (PMID 26106036, 2015). "Repeating the analysis but censoring at the first cancer yielded similar results (eg, under the polygenic model BRCA1 mutation frequency was estimated to be 0.083% and BRCA2 mutation frequency was 0.27% with a polygenic SD of 1.46)." (PMID 26025000, 2015). "For BRCA1- group we observed a significant increase in cancer risk for the heterozygotes carrying silent polymorphism p.Ile1145 = in the ABCB1 gene (OR 1.64; 95% CI 1.03-2.60; p = 0.036)." (PMID 25591549, 2015). "The most straightforward strategy to select patients is to obtain the mutation status of BRCA1/2 in cancer specimens." (PMID 25852742, 2015). "In the present study, miRNA expression profiles were investigated by miRNA microarray between normal and cancer tissue from BRCA1 and BRCA2 germ-line mutation carriers, in comparison with normal tissue from non-carriers." (PMID 26378051, 2015). "Analysis of LoF PPVs in genes that cause diseases other than cancer identified genetic risks in 19 of the 176 (10.8%) BRCA1/2-carriers." (PMID 26023681, 2015). "In recent years, it has been further linked to chromatin alterations in cancer, including recruitment to sites of DNA repair, indicating a direct function of BRCA1 in transcriptional control through chromatin structure modulation." (PMID 25879655, 2015). "As compared to BRCA1 mutated cases (20/38; 52.6%) significantly fewer sporadic cancers (19/86; 22.1%) expressed TRβ (p = 0.001)." (PMID 26029931, 2015). "A computer model was used to calculate the long-term effect of this screening on cancer incidence by assessing both the mutation detection rate and the completion of prophylactic surgeries in BRCA1/2 mutation carriers." (PMID 26870808, 2015). "PARP inhibitors have shown promising clinical results in cancer patients carrying BRCA1/2 mutations." (PMID 26354718, 2015). "It is conceivable that cancers with low 53BP1 expression have a co-existing defect in the BRCA1 pathway given that 53BP1 loss is frequently observed in BRCA-deficient cells." (PMID 25586219, 2015).
cancer (continued). "These included homozygous variants calls in genes related to cancer (BRCA1, APC, MEN1), congenital malformation syndromes (TCOF1), metabolic deficiencies (FBP1, HEXA), and neurological diseases (FUS, MLC1, DMD)." (PMID 26547235, 2015). "Recently, it has been suggested that BRCA1 gene heterozygosity suffices for cancer predisposition, by triggering genome instability that accumulates over many cell divisions." (PMID 25992773, 2015). "It is currently under trial as single agent and in combination therapy with chemo and radiotherapy (RT) in a plethora of different types of cancer such as advanced solid malignancies and deleterious BRCA1/2 mutation-associated cancers (clinicaltrials.gov)." (PMID 26610585, 2015). "A hallmark of BRCA1/2-mutated carcinomas is their hypersensitivity to platinum-based chemotherapy and PARP inhibitors." (PMID 26426684, 2015). "The initial expectation that HIF-1α should be increased in TNBC comes from its high documented levels in hereditary BRCA1 mutated carcinomas (up to 90% of cases)." (PMID 26046764, 2015). "The basal-like subtype is a highly aggressive carcinoma that is often resistant to chemo- and hormonal therapy and has an increased occurrence in patients with germline BRCA1 mutations or in patients of African ancestry." (PMID 26517092, 2015). "In this review, we summarize the current research and our view of how PTEN and BRCA1 function with their partners to transduce signals downstream and what are the implications for cancer-associated biology." (PMID 25426449, 2014). "In this study, we investigated tumor progression mathematically and the evolution of resistance to platinum drugs and PARPis in BRCA1/2-mutated cancers before and during treatment." (PMID 25158060, 2014). "Defects in the DNA damage response or in the DNA repair pathways in patients with the BRCA1/2 mutation are responsible for the high penetrance of these cancers in the breast and/or ovary." (PMID 25429284, 2014). "The use of another BRCA1/2 associated cancer model, and the quite large number of available patient samples represent the strengths of this study." (PMID 25036526, 2014). "PARP inhibition is preferentially cytotoxic to cancer cells with BRCA1 and BRCA2 mutations, but that effectiveness is reduced in cells with intact BRCA function." (PMID 24784564, 2014). "In vitro and in vivo evidence has supported the utilization of PARP inhibitors as single agents to reduce cancer cells that possess a defect in DNA repair that additionally have BRCA1 and BRCA2 mutations." (PMID 24317580, 2014). "It is therefore highly important to identify the cancer predisposition defects of the unsolved high-risk non-BRCA1/2 families." (PMID 24479546, 2014). "PARP inhibitors are currently being evaluated in clinical trials because of the synthetic lethality caused in cancers with genetic makeups that renders HR repair inactive, such as BRCA1 or BRCA2 mutations." (PMID 25074383, 2014). "For example, PARP inhibitors have been shown to induce synthetic lethality to cancer cells with BRCA1 or BRCA2 mutations." (PMID 24465681, 2014). "In the case of increased odds of cancer, past research suggested that having low numbers of CGGs rescued embryos carrying the BRCA1/2 mutation, an example of a direct biological mechanism." (PMID 25250047, 2014). "This study integrated qualitative data from three independent investigations of BRCA1/2-positive women recruited through cancer risk clinics, hospital-based research centers, and online organizations." (PMID 24586286, 2014). "BRCA1 loss in mammary epithelium therefore alters the estrogenic growth response, and increased estrogen signaling collaborates with Brca1 deficiency to accelerate preneoplasia and cancer development." (PMID 24478985, 2014).